CD4 (CD4 molecule)
Diseases named in the same sentence as CD4 in open-access papers (continued):
Sharing a sentence is not in itself a finding about the gene and the disease.
tumor (continued). "Surgical trauma and tumor microenvironments can suppress the innate immunity of patients, as well as increase the postoperative infection rate and tumor metastasis by inducing CD4+ T cells toward a T-helper 2 (Th2) cell fate." (PMID 34414234, 2021). "The anti-tumor response of CD8+T cells is canonically supported by CD4+Th1 helper cells." (PMID 34095125, 2021). "Moreover, functional tumor-infiltrating Tfh cells (CD4+ IL-21+) correlated positively with the infiltration of CD138+ plasma cells." (PMID 34359579, 2021). "However, the distribution of CD8+ and CD4+ T cells detected by immunofluorescence staining in different regions of the tumor revealed that higher numbers of CD8+ T cells accumulated in the center of tumors from WT mice than Apelin-KO mice." (PMID 34234274, 2021). "In the environment of OC cells, CD4+ Tregs mainly take the way of glycolysis for energy metabolism, and consume more energy than the effector cells, inhibiting the function of the effector cells to promote tumor growth." (PMID 33414414, 2021). "Like CD8+ T cells, CD4+FoxP3+ Treg cell infiltration was low in all treatment groups, but both age and stress effects were revealed, as well as relationships with circulating corticosterone and CD4+ T cell and macrophages tumor infiltration." (PMID 34604038, 2021). "Resting CD4+ memory T cells maintain immune memory and exert immune protection during tumor metastasis, and M2 macrophages can also promote tumor growth and metastasis." (PMID 35252217, 2021). "Moreover, if tumor antigen recognition by CD4+ is relevant for outcomes, these tumor antigens should be restricted by MHC class II, and this would predict an association between MHC class II expression and beneficial clinical outcomes." (PMID 34910940, 2021). "Indeed, the IL-1β secreted in the tumor microenvironment induces the secretion of IL-17 through its effect on CD4 T cells, by driving the differentiation and expansion of Th17 cells, which promote angiogenesis and tumor growth via the STAT3 signaling pathway." (PMID 33498483, 2021). "Immuno-elevating effect of SYY could reverse secreting TGF-β1 and recruiting Tregs or differentiating CD4 process, consequently suppressing tumor growth and metastasis." (PMID 33801741, 2021). "In fact, a significant proportion of tumor-infiltrating CD4 + cells are Tregs." (PMID 34095125, 2021). "For example, the mean normalised values of CD3 (MGMTuc = 8.04 [1.02] and MGMTmc = 8.90 [0.61]) and CD4 (MGMTuc = 9.58 [1.01] and MGMTmc = 11.22 [0.65]) may indicate very low levels of T-cells and T-helper cells, respectively, within the tumours." (PMID 33995529, 2021). "Promote the differentiation of naive CD4+ T cells into Tregs and facilitate tumor immune escape." (PMID 34737750, 2021). "Therefore, we analyzed the correlation of NCOA4 expression with six kinds of infiltrating immune cells (CD8+ T cells, CD4+ T cells, B cells, dendritic cells macrophages, and neutrophils) and tumor purity." (PMID 33402128, 2021). "CD4+ T helper cells can either inhibit or promote tumour cell survival." (PMID 33860061, 2021). "In the cohort with large samples, TCGA and GSE31210, low-risk group had higher proportions infiltrating of activated CD8 T cells, effector memory CD8 T cell, central memory CD4 T cell, type 1 helper T cell and activated B cell, which play an important role in anti-tumor immunity." (PMID 35069695, 2021). "Indeed, two DNA vaccines targeting TA have been reported with antitumor effect through increasing antigen-specific CD4+ or CD8+ T cells in tumor-bearing mice." (PMID 34611173, 2021). "Compared to traditional IL-2, NKTR-214 does not cause significant amplification of CD4+ Foxp3+ Tregs, and thus, has greater anti-tumor activity and fewer adverse effects." (PMID 33746989, 2021). "Also, along with the relatively low levels of CD4+ T cells in the tumor samples with high scores, were relatively low levels of the T helper subsets Th2 and Th17." (PMID 34630508, 2021).
tumor (continued). "Furthermore, shifts in methylation patterns of Th1 CD4 + T cells after NACT show a relocation of cells from blood to the tumor." (PMID 33761971, 2021). "However, the functional diversity of CD4+ T cells and disorders of CD4+ T cell subsets weaken the anti-tumor responses." (PMID 33791306, 2021). "Moreover, the number of tumor infiltrating CD4+ and Foxp3+ lymphocytes were independent prognostic factors for survival in BTC." (PMID 34573939, 2021). "Also, we measured total WNT5A mRNA levels by qPCR in the tumor cell fraction (CD4 + /CD7 − /CADM1 +) of an HTLV-1 carrier, a smoldering-type ATL patient, and 3 acute-type ATL patients, which were concentrated by the HAS-Flow method." (PMID 33603066, 2021). "Tregs cells can attenuate the anti-tumor effects of CD4 T, CD8 T, and NK cells." (PMID 34552612, 2021). "Notably, the expression of IL-2 mRNA in the CD44hi donor CD4+ T cells of the AAA-CD4+ group dramatically increased (7-fold) within the tumor 24 h after injection, relative to 4 h after injection, while IL-2 mRNA was not increased in the auto-CD4+ group." (PMID 34625113, 2021). "The T anti-tumor response mediated by the CD4 helper T cells and the CD8 cytotoxic cells are regulated by endogenous factors and other cells, such as Th17, Treg, MDSCs, etc., that will ultimately result in either a positive anti-tumor response or an immuno-suppressive response." (PMID 34685635, 2021). "They found that tumor-derived IgG, which was purified from ovarian cancer tissue, could suppress the proliferation of CD4+ or CD8+ T cells derived from cord blood monocyte cells and cord blood lymphocyte (CBL)." (PMID 34226529, 2021). "In addition, we explored the CD40 ligand (CD40L) expression on T cells in the tumor microenvironment and found that ~ 50% and ~ 10% of CD4+ Th cells express CD40L in the YUMM3.3 and B16F10 tumors, respectively." (PMID 34092233, 2021). "Interestingly, VEGFR-2 blockade predominantly upregulated PD-L1 expression in HCC cells and increased the PD-1 expression in tumor-infiltrating CD4+ T cells via interferon-gamma of the endothelial cells paracrine." (PMID 34899747, 2021). "During the pre-malignant phase of tumor development it has been shown that senescence surveillance is the driving force for the elimination of pre-cancerous and senescent hepatocytes with a secretory phenotype by CD4 T cells and macrophages." (PMID 34209393, 2021). "Additionally, different studies have also proved that activated memory CD4+ T cells were the key instruments of tumor cure." (PMID 33763372, 2021). "The distinct CD4+ T-cell subsets have diverse impact on tumor growth." (PMID 34680248, 2021). "In summary, pro-tumor factors include high type II M2 macrophages; high CD4+ regulatory T cells (Tregs); high type II CD4+ Th2 cells; typically low or exhausted tumor infiltrating lymphocytes (TILs) (cold tumor); and low antigenicity and immunogenicity of the tumor cells." (PMID 33535484, 2021). "This study revealed that the TME may induce epigenetic alterations in tumor infiltrating CD4+ T cells." (PMID 34262562, 2021). "CD4+ T cells harbor a crucial role for effective antitumor immunity and could further improve and sustain T cell reactivity and tumor clearance." (PMID 33583769, 2021). "This was observed when CD4 depletion was carried out during the priming phase alone, or throughout the entire experiment including the effector phase (i.e. post tumor challenge)." (PMID 34741035, 2021). "Additionally, in the presence of CCL2 produced by CAFs, TAMs, and tumor cells, cytotoxic TILs acquire a CD4+CD25+ Tregs phenotype, which leads to secretion of the immunosuppressive transforming growth factor-beta (TGF-β) and IL-10." (PMID 33922362, 2021). "PB Treg enrichment observed at tumor induction may create conditions supporting CD4 T cell senescence-mediated systemic immune suppression." (PMID 34502204, 2021). "CD4 + T cells play an important role in maintaining tumor immunity." (PMID 33718128, 2021).
tumor (continued). "We implied that the expression level of HSPA7 was moderately positively associated with degree of macrophage, neutrophil, CD4+ T cells and DC infiltration, and weakly positively correlated with the degree of B cells and CD8+ T cells infiltration in KIRC tumor tissues." (PMID 34412642, 2021). "A number of recent studies have demonstrated an important role for CD4 T cells in tumour control." (PMID 34858415, 2021). "Investigating these clusters in Kaluza (software version 2.1) revealed an association between tumor stage and CD279- naïve CD8+ T cells, CD279+ CD8+ TCM, CD279+ CD8mid TEM and CD279+ CD8mid TCM as well as CD279high CD4+ TCM." (PMID 34868015, 2021). "Moreover, we found cells co-expressing IL-17A and CD4 both in the stroma and tumor regions, which accounted for 22% and 17% of all IL-17A+ cells, respectively, and for 2% and 6% of all CD4+ cells, respectively." (PMID 34944746, 2021). "Our results suggest that GBM might induce epigenetic alterations in tumor infiltrating CD4+ T-cells there by influencing anti-tumor immune response by manipulating differentiation and function of tumor infiltrating CD4+ T-cells." (PMID 34012510, 2021). "The therapeutic effect was associated with increased percentages of CD8+ T cells at the tumor site, indicating that other subsets of T cells, including CD4+ T cells and Tregs, may have limited roles during CTLA-4 blocking antibody cancer therapy." (PMID 33800368, 2021). "The HLA class II expression of human tumor cells may contribute to an enhanced tumor immunity, since it can induce HLA class II-restricted CD4+ T-cell responses." (PMID 34359808, 2021). "In addition, STOT provides information about the cellular composition of the tumor microenvironment, particularly when CD4 and CD8 are added to the CD3, CD19, CD45, CD56, and CD271 markers." (PMID 34638431, 2021). "The visualization of exhausted BTLA+ CD4+ T cells in plaques consistently revealed their presence within the vicinity of malignant, NK, CD8+, and effector CD4+ T cells, and their densities each significantly increased in the transition from plaque MF to tumor MF." (PMID 34885092, 2021). "Whole-genome bisulfite sequencing of tumor infiltrating and blood CD4+ T-cell from GBM patients showed 13571 differentially methylated regions and a distinct methylation pattern of methylation of tumor infiltrating CD4+ T-cells with significant inter-patient variability." (PMID 34012510, 2021). "Finally, the density of IL-4+ TOX+ CD4+ T cells and the levels of expression of these molecules significantly marked lesion progression from plaque to tumor." (PMID 34220814, 2021). "Between GBM-associated antigen-targeting CD4+ and CD8+ CAR-T cells, CD4+ CAR T cells showed effector persistency after tumor challenge and similarly in orthotopic GBM model, CD4+ CAR-T outcompeted CD8+ CAR-T in terms of durable anti-tumor response." (PMID 34012451, 2021). "Interestingly, inhibition of the histone H3K27 methyltransferase enhancer of zeste homolog 2 (EZH2) activity in Tregs induces Treg-mediated pro-inflammatory functions, enhancing IFNγ production by CD8+ and CD4+ Th1 cells and anti-tumor immune responses." (PMID 33801234, 2021). "Intriguingly, Chen and colleagues demonstrated that expression of stress-inducible HSP90α on the surface of tumor-cell released autophagosomes (TRAPs) promotes IL-6 production by CD4+ T cells via TLR2-Myeloid differentiation primary response protein 88 (MyD88)- NF-kB signalling pathway." (PMID 34917098, 2021). "It is now well established that long peptide vaccines are preferred to single CD8 epitopes due to their capacity to harbour multiple CD8+ and CD4+ T cell epitopes and bind to a wider range of HLA-haplotypes, thereby increasing their efficiency at generating durable anti-tumour responses." (PMID 34262856, 2021). "Thus, in further studies, analyses of CD4+ subsets would be crucial in establishing their role in tumor progression." (PMID 34952631, 2021).
tumor (continued). "It is now accepted that CD4 T lymphocytes play an essential role in the anti-tumor response." (PMID 33498483, 2021). "The reduction in central memory CD4+ T cells may be attributed to their reactivation, differentiation, and migration to the tumor." (PMID 36405502, 2021). "However, the potential of CD4+ helper T (Th) cells in tumor suppression has recently gained attention in the field of immunotherapy." (PMID 34899753, 2021). "However, for CAR T cells, CD4+ T cells possess direct anti-tumor activity comparable to cytotoxic CD8+ CAR T cells." (PMID 34503109, 2021). "Further studies into the application of CD4+ GzmB+ T cells in tumor immunotherapy are needed." (PMID 34631551, 2021). "Whether anti-tumor CD4+ and CD8+ T cells engage selectins in tumors and whether these interactions contribute to T cell exhaustion is unknown." (PMID 33708224, 2021). "The simultaneous prominence of the three types cells, CD8+ T cells, activated CD4+ memory T cells and M1 macrophages, implying that co-mutation of FAT3 and LRP1B can be used to predict the cytotoxic effect of lymphocytes against tumor cells and the beneficial response of immunotherapy in LUAD." (PMID 35069585, 2021). "Cytotoxic CD8+ T cells, which are activated by helper CD4+ T cells, may enter the tumor microenvironment and induce apoptosis, resulting in shrinkage of the tumor lesions." (PMID 34164110, 2021). "Thus, the proportion and the absolute number of CD4+ CD25+ T cells significantly increase in the area surrounding the tumor, and Tregs increased in the peripheral blood of HCC patients compared to healthy subjects." (PMID 34071550, 2021). "FGL1 silencing accelerates CD8+ and CD4+ T cell immunity against tumor growth." (PMID 33867830, 2021). "Furthermore, this study showed that CD4+ T cell neo-epitope vaccination induced CD8+ CTL responses against an independent tumor antigen in the vaccinated mice, possibly due to the occurrence of an “antigenic spread” in the vaccinated mice." (PMID 34207062, 2021). "The results from the TIMER database suggested that ACSS2 was remarkably correlated not only with tumor purity but also with the infiltrating levels of different immune cells, including CD4+ T cells, CD8+ T cells, B cells, neutrophils, macrophages, and dendritic cells, in CESC." (PMID 34206705, 2021). "Indeed, CD4+ T cells are recognized to be essential for tumor immunity as they can exhibit direct cytotoxicity against tumor cells as well as potentiate DC resulting in enhanced CD8+ T cell responses." (PMID 33679807, 2021). "The accumulation of CD4+ T cells positively correlates with tumor-specific immune response." (PMID 33902630, 2021). "Since, DNA methylation is involved in silencing (or releasing gene suppression upon demethylation of promotor regions) gene expression at the transcription level, one would assume that GBM regulate the expression of the genes in tumor infiltrating CD4+ T cells by modulating their DNA methylation." (PMID 34012510, 2021). "CD4/CD8 ratio shifted after T cell transplantation, CD8+ CTLA4-T cells were growing faster in vivo, higher CD8+ T cell percentage was associated with higher anti-tumor efficacy." (PMID 33868277, 2021). "The relationship between CD4+ TILs in tumor site and prognosis was controversial." (PMID 33793095, 2021). "On the other hand, neutrophils might also suppress the anti-tumor immune mechanisms by suppressing both natural killers and CD4+ and CD8+ T cells." (PMID 34501353, 2021). "Priming and activation of tumor antigen-specific CD4+ and CD8+ lymphocytes occur in LNs; accordingly, LNs samples may be useful in studying cancer immunology." (PMID 32808188, 2021). "However, there is evidence of the importance of CD4+ activity in generating an anti-tumour response directly with so called cytotoxic CD4+ T cells." (PMID 34276688, 2021). "In addition, we found that CD4+ T cells were able to induce inflammatory activation of myeloid cells to substantially impair tumor growth." (PMID 34283809, 2021).
tumor (continued). "Our current studies are in agreement with these findings, in that tumor-primed CD4+T cells following high salt activation demonstrated a three times higher level of glycolytic reserve and 1.8 times higher basal mitochondrial oxidation, as compared to equimolar mannitol control stimulation." (PMID 33918403, 2021). "Healthy C57BL/6 mice that were vaccinated with the MC-38 fusion cell membrane-coated nanoparticles for two consecutive weeks before MC-38 tumour cell inoculation revealed to have benefitted from significant anti-tumour protection with enhanced infiltration of CD4+ and CD8+ T cells in the tumour." (PMID 34443638, 2021). "Indeed, the treatment increased the number of granzymeB+ and interferon ɣ (INFɣ)+ CD8+T cells in the tumor mass and the percentage of circulating activated CD4+, CD8+ T cells, and NK cells." (PMID 33800368, 2021). "Intriguingly, SERDs (either fulvestrant or JD128), despite lacking a direct antitumor effect on ER-negative BC, were found to reduce the counts of MDSCs and Tregs as well as increase the infiltration of DCs and CD8 + and CD4 + T cells in 4T1 tumor-bearing mice." (PMID 33413549, 2021). "Furthermore, IFN-γ induces the expression of IL-12 and IL-15 in DCs, which induces anti-tumor responses through CD4+ TH1 and CD8+ T cells." (PMID 34439191, 2021). "CD4+ T cells can eliminate tumor cells by promoting the functions of CTLs or modulating the TME." (PMID 35087741, 2021). "PD-1 is mainly expressed by CD4+ and CD8+ T lymphocytes whereas its ligand, PD-L1 is widely expressed in various cell types including activated lymphocytes, fibroblasts, tumor-associated macrophages, and tumor cells." (PMID 34966689, 2021). "Considering the upregulated PD-1 expression in tumor-infiltrating CD4+ and CD8+ T-cells of Nhe1 KO mice, we tested whether these mice were more sensitive to TMZ plus anti-PD-1 combinatorial therapy." (PMID 33391535, 2021). "Human tumor expression of CD47 has been shown to correlate with the expression of various co-inhibitory markers, such as program cell death protein 1 (PD-1) and cytotoxic T-lymphocyte associated protein 4 (CTLA-4), on tumor-infiltrating CD4+ and CD8+ T cells." (PMID 34603322, 2021). "Thus, our data support the observation that both CD4+ and CD8+ T cells are critical for efficient anti‐tumor immunity and are implicated in driving responses to immunotherapy." (PMID 33755340, 2021). "Cytotoxic CD4+ effectors, with anti-tumor activity, was identified by other researchers in other tumors, and might lead to therapeutic benefit." (PMID 33648605, 2021). "In more detail, the TME is populated by infiltrating cells such as cancer-associated fibroblasts (CAFs), tumor-associated macrophages (TAMs), endothelial progenitor cells (EPs), mast cells (MCs), mesenchymal stem cells (MSCs), T lympohocyte (CD4, CD8, CD4, Tregs), and platelets." (PMID 34439343, 2021). "infection and tumor-infiltrating lymphocytes (especially CD4 + T cells), which could be affected by MSI status 20-22." (PMID 33442401, 2021). "Importantly, we found that DMXAA treatment significantly increased the proportion of (CD11b− CD3+) CD8+ T cells without significantly changing the proportion of (CD11b− CD3+) CD4+ T cells in the bone marrow tumor microenvironment." (PMID 34315904, 2021). "Additionally, activation of PD-1 in naïve CD4+ T cells induces their conversion to immunosuppressive CD4+ FoxP3+ T regulatory cells (Tregs) which, in a juxtracrine and paracrine manner, inhibit anti-tumour immune responses." (PMID 34299373, 2021). "Notably, a large increase in CD4+ T lymphocytes was observed for tumour T4 (25.7% to 76.8%) and in CD8+ T lymphocytes in tumours T2 (4.5% to 21.4%) and T3 (2.7% to 11.9%)." (PMID 34503115, 2021). "Meanwhile, CSRNP2 and CSRNP3 were both mostly positively associated with effector memory CD4 T cells, but not with type 2 T cells in tumor tissues." (PMID 33869003, 2021).